ENSG00000257921 (novel protein)
Gene: Protein-coding gene on chromosome 12 (57,772,660 to 57,797,554, forward strand). Ensembl gene ENSG00000257921.
Genetic constraint (gnomAD): Loss-of-function variants: 17 observed, 15.01 expected, observed/expected ratio (o/e) 1.13, 90% interval 0.77 to 1.68. Missense variants: 139 observed, 142.04 expected, observed/expected ratio (o/e) 0.98, 90% interval 0.85 to 1.13. Synonymous variants: 70 observed, 58.61 expected, observed/expected ratio (o/e) 1.19, 90% interval 0.98 to 1.46.